IL7R (interleukin 7 receptor)
Diseases named in the same sentence as IL7R in open-access papers (continued):
Sharing a sentence is not in itself a finding about the gene and the disease.
colorectal cancer (6 papers, 2015 to 2025). A primary or metastatic malignant neoplasm that affects the colon or rectum. "Genes upregulated in Arm A as compared to Arm B include IL7R, a key receptor for the survival and proliferation of naive and memory T cells, and GZMK, a cytotoxic molecule associated with poor prognosis in colorectal cancer." (PMID 39811671, 2025).
Granuloma (6 papers, 2020 to 2025). A compact, organized collection of mature mononuclear phagocytes, which may be but is not necessarily accompanied by accessory features such as necrosis. "Pathway analysis also identified interleukin-7 receptor alpha (IL7Rα) as an upstream regulator in granulomas compared to control samples." (PMID 40521183, 2025). "We also found that α-MSH exerts anti-inflammatory effects on this granuloma model with a clear reduction of IL-7, IL-7R, and IFN-γ." (PMID 32350353, 2020). "A significant increase in IL-7, IL-7R, and IFN-γ protein expression was found in developed granulomas comparing to microparticle unchallenged PBMCs." (PMID 32350353, 2020). "IL-7, IL-7R, and IFN-γ protein expression was significantly reduced in developed granulomas after exposure to α-MSH compared with saline treated granulomas." (PMID 32350353, 2020). "The most abundant subcluster (8.3% of granuloma cells, q = 0.074, Dirichlet p = 0.00049) exhibited elevated expression of markers of naive and memory T cells (TCF7, CCR7, IL7R, and TXNIP) and activation or memory state (CD69 and ITGB1)." (PMID 35483355, 2022).
lymph node metastasis (6 papers, 2010 to 2024). "Although no clinicopathological factors were significantly associated with high expression levels of IL-7R, histological grade, depth of tumor invasion, lymphatic invasion, vascular invasion, and lymph node metastasis tended to be related to the expression levels of IL-7R in patients with ESCC." (PMID 36672342, 2023). "But patients with higher tumor size, FIGO stage, and lymph node metastasis (LNM) have more high-expressed Lnc-IL7R." (PMID 29720427, 2018). "Up-regulated Lnc-IL7R positively correlated to tumor size, International Federation of Gynaecology and Obstetrics (FIGO) stage, and lymph node metastasis (LNM)." (PMID 29720427, 2018).
neuroblastoma (6 papers, 2014 to 2025). Neuroblastoma (NB) is the most common solid, extracranial childhood tumor. "With the exception of ID2, all the other immune genes (CD8a, IL2, IL7R, IL6, ID3, and CXCR3) were also highly expressed in low-risk neuroblastoma patients further confirming the significance of these immune genes in neuroblastoma cases with favorable outcomes." (PMID 36068918, 2023). "Coexpression with IL-7R in CAR-T cells sustains signaling upon antigen recognition while sparing bystander lymphocytes, with early clinical trials (NCT04099797, NCT03635632) evaluating IL-7R-expressing GD2 CAR-T cells in brain tumors and refractory neuroblastoma." (PMID 40481182, 2025).
ovarian carcinoma (6 papers, 2013 to 2026). A malignant neoplasm originating from the surface ovarian epithelium. "Currently, the specific mechanisms underlying the functions of IL-7 and its receptor (IL7R) in the ovarian cancer TME remain unclear." (PMID 41360767, 2025). "Thus, we speculate that ovarian cancer cells expressing IL7R have a close association with tumor-associated macrophages in the immune microenvironment." (PMID 41360767, 2025). "In conclusion, this study clarifies how IL7R signaling mediates crosstalk between ovarian cancer cells and macrophages to maintain the homeostasis of the immunosuppressive tumor microenvironment (TME)." (PMID 41360767, 2025). "Multiplex immunofluorescence staining confirmed that human ovarian cancer tissues with high IL-7R expression exhibited an “immune desert” phenotype, where immune cells were predominantly localized at the tumor periphery." (PMID 41360767, 2025). "In this study, we elucidated the role of the IL-7/IL-7R axis in the ovarian cancer microenvironment and identified IL-7R expression in tumor cells as a critical target for the regulation of IL-7 signaling." (PMID 41360767, 2025). "In summary, IL7R-expressing ovarian cancer cells promote the immunosuppressive state of TAMs, thereby facilitating the establishment of an immunosuppressive microenvironment." (PMID 41360767, 2025). "This study demonstrated that IL-7R plays a pivotal role in remodeling the immune microenvironment of ovarian cancer, primarily by regulating the infiltration patterns of immune cells and the polarization of macrophages." (PMID 41360767, 2025). "From the perspective of clinical translation, our research supports the potential of targeting IL7R as a novel therapeutic strategy for ovarian cancer, particularly when combined with immunotherapies that modulate macrophages." (PMID 41360767, 2025). "This study demonstrated that increased IL7R expression in ovarian cancer is correlated with the polarization of CD206+ macrophages, the remodeling of the immunosuppressive microenvironment, and unfavorable patient prognosis." (PMID 41360767, 2025). "In human ovarian cancer tissues, regions with high IL7R expression were significantly enriched in CD206+ TAMs." (PMID 41360767, 2025). "Multiplex immunofluorescence staining of human ovarian cancer tissues revealed that tumors with high Il7r expression showed restricted immune cell infiltration, which was mainly localized at the tumor periphery, with minimal immune cells present in the tumor core." (PMID 41360767, 2025). "However, the present study documents an opposing effect in ovarian cancer: endogenous IL-7/IL-7R signaling promotes disease progression by driving tumor cell-autonomous proliferation and the formation of an immunosuppressive microenvironment." (PMID 41360767, 2025). "Subsequently, consistent results were also observed in ovarian cancer tissues of mice inoculated with Il7r-WT or Il7r-KO cells: specifically, the expression of CD206 in TAMs was significantly enhanced in the TME of ovarian cancer with IL7R-expressing tumor cells." (PMID 41360767, 2025). "Collectively, these findings demonstrate that IL7R signaling in ovarian cancer cells drives the remodeling of the immunosuppressive microenvironment and promotes the polarization of macrophages toward an immunosuppressive state (characterized by the CD206+ phenotype)." (PMID 41360767, 2025). "In this study, a physiologically relevant 3D bioprinted platform and animal models were used to demonstrate that ovarian cancer cells expressing IL7R induce remodeling of the tumor immune microenvironment and promote the polarization of macrophages toward an anti-inflammatory phenotype." (PMID 41360767, 2025). "Notably, TRM cells in ovarian cancer show features of activated T cells, such as an elevated surface expression of HLA-DR coupled to the downregulation of CD127 (IL-7Rα), and the co-expression of the proliferation marker Ki67." (PMID 36385379, 2022).
ovarian carcinoma (continued). "Additionally, IL7R was stably expressed across four human ovarian cancer cell lines, indicating that these cells may be responsive to circulating IL-7." (PMID 41360767, 2025). "Meanwhile, we analyzed the correlation between IL7R expression and PFS in patients with low-grade and high-grade ovarian cancer who had undergone optimal debulking surgery." (PMID 41360767, 2025). "We subsequently analyzed the correlation between IL7R expression and progression-free survival (PFS) in early-stage and late-stage ovarian cancer patients who had undergone optimal debulking surgery." (PMID 41360767, 2025). "Notably, the primary source of IL-7 in ovarian cancer may be the systemic circulation rather than the tumor microenvironment itself, which further amplifies the dominance of IL-7R-positive tumor cells in regulating the microenvironment." (PMID 41360767, 2025). "Among the genes we identified in this study, IL7R, IRF8, PTPRC, and NSG1 have not been thoroughly explored or recognized for their relevance in ovarian cancer recurrence in previous studies." (PMID 41596598, 2026).
pulmonary fibrosis (6 papers, 2018 to 2024). Chronic progressive interstitial lung disorder characterized by the replacement of the lung tissue by connective tissue, leading to progressive dyspnea, respiratory failure, or right heart failure. "We demonstrated that IL-7 neutralization in the lung was effective in alleviating CS-induced pulmonary fibrosis by decreasing pathogenic CD4+ TRM-Teff cells but not TRM-Tregs expressing low IL-7R." (PMID 39122899, 2024). "Thus, there is already evidence that IL7R, LBH, and CXCR6 are important for understanding processes that promote pulmonary fibrosis, and LRRC39 and PLBD1 are additional targets for future studies." (PMID 35715807, 2022). "Five genes demonstrated concordant directions of effects between the ILA [IPF transcripts] and IPF scores (CXCR6, IL7R, LBH, LRRC39, PLBD1), suggesting these genes may represent important biologic processes in promoting the progression of pulmonary fibrosis." (PMID 35715807, 2022).
dermatitis (5 papers, 2015 to 2025). An inflammatory process affecting the skin. "For example, a cis-sQTL for the transmembrane domain splicing of IL7R colocalized with an association locus for dermatitis and eczema, as well as a pQTL for IL-7R in UKB-PPP." (PMID 40038547, 2025). "The alternative allele of rs6897932 (T) is associated with decreased excision of the IL7R transmembrane domain, lower levels of IL-7R in plasma and reduced risk of dermatitis and eczema." (PMID 40038547, 2025). "Meanwhile, in the lesional (dermatitis) tissue, both IL-7Rα+ and perforin+ CD8+ T cells were increased." (PMID 28791017, 2017). "Ruxolitinib cream ameliorated dermatitis symptoms by modulating the transcription of genes directly involved in TSLP signaling, such as IL-7 receptor (Il7r) and JAK-STATs." (PMID 33658996, 2020). "This idea is supported by the finding that perforin+ CD8+ T cells, which represent IL-7Rαlow EM CD8+ T cells, were increased in dermatitis affected, rather than IL-7Rα+ CD8+ T cells." (PMID 28791017, 2017).
endometriosis (5 papers, 2010 to 2025). The growth of functional endometrial tissue in anatomic sites outside the uterine body. "Our results show that several mRNAs and pathways related to immune function, such as IL-1B, CXCR4, IL-7R, STAT4, CD14, and CCR5, as well as the FoxO signaling pathway, the Jak-STAT signaling pathway, and the NF-kappa B signaling pathway, have significant correlations with endometriosis." (PMID 38203209, 2023).
glioblastoma (5 papers, 2020 to 2025). The most malignant astrocytic tumor (WHO grade IV). "It has been shown that engineered T-cells constitutively expressing the IL-7 receptor alpha (IL-7Rα) have great antitumor efficacies in both breast cancer and glioblastoma models, therefore, IL-7 and its receptor are great candidates for immunotherapy." (PMID 41208963, 2025). "Our study demonstrated the therapeutic potential of IL7Rα-incorporating CAR-T cells for glioblastoma treatment, suggesting a promising strategy for augmenting the effectiveness of CAR-T cell therapy." (PMID 38619641, 2024). "We constructed B7H3-targeting CAR structures composed of three different lengths of the IL7Rα signaling domain and assessed their antitumor activities against glioblastoma in vitro and in vivo." (PMID 38619641, 2024). "It is worth noting, that in a recent pre-clinical study, B7-H3 CAR-T cells consisting of IL-7Rα, have been shown to suppress tumor growth and prolong overall survival in glioblastoma mouse models, suggesting the potential implication of B7-H3-IL-7Rα CAR-T cells in the clinic." (PMID 41208963, 2025). "Our results demonstrated that these intrinsic IL7Rα-CAR-T cells exhibit enhanced antitumor activity and T-cell persistence against glioblastoma compared with conventional 2nd generation B7H3 CAR-T cells." (PMID 38619641, 2024).
hepatitis C virus infection (5 papers, 2017 to 2024). A viral infection caused by the hepatitis C virus. "TRAF1 expression is positively correlated with the expression levels of IL-7R, myeloid cell leukemia-1, and CD107a and is involved in supporting specific CD8+ T cell responses during hepatitis C virus infection." (PMID 38995016, 2024).
pancreatic cancer (5 papers, 2020 to 2023). "Indeed, we have analyzed the ability of differential diagnostic power with levels of IL-7R among healthy subjects, pancreatic cancer, and other pancreatic diseases (e.g., chronic pancreatitis) for a large-scale validation and found the higher differential levels between the diseases." (PMID 34575268, 2021). "Differentially expressed mRNA in PBMC was analyzed in human healthy subjects and pancreatic cancer patients to reveal the positive correlation between IL-7R expression in PBMC and pancreatic cancer utilizing transcriptome analysis." (PMID 34575268, 2021). "IL-7R positive cells were significantly increased in PBMCs from pancreatic cancer patients compared with PBMCs from healthy donors." (PMID 34575268, 2021). "We found that protein expression of IL-7R was rapidly increased from the early stages of the onset of tumor formation in orthotopic pancreatic cancer mouse model in vivo and identified the discrete subset of IL-7R expressing cells." (PMID 34575268, 2021). "We showed that IL-7R expression in pancreatic cancer patients was elevated compared to healthy human subjects." (PMID 34575268, 2021). "We then compared the percentage of IL-7R+ in these cells between pancreatic cancer patients (n = 6) and other disease patients (n = 8)." (PMID 34575268, 2021). "IL-7R expressing cells rapidly appeared from the early stages of the onset of tumor formation in syngeneic pancreatic cancer mouse model in vivo." (PMID 34575268, 2021). "We here showed that IL-7R+ cells in PBMCs rapidly appeared from the early stages of the onset of tumor formation in syngeneic pancreatic cancer mouse model in vivo and the expression of IL-7R was significantly elevated in pancreatic cancer patients compared to healthy individuals." (PMID 34575268, 2021). "Notably, IL-7R expression was significantly up-regulated in PBMCs from pancreatic cancer patients in comparison of those of healthy donors, indicating that IL-7R mRNA expression is elevated in PBMC from patients with pancreatic cancer." (PMID 34575268, 2021). "Moreover, IL-7R in PBMC was highly expressed in patients with pancreatic cancer compared to healthy donors." (PMID 34575268, 2021). "IL-7R positive cells were measured in PBMCs from pancreatic cancer patients and healthy donors." (PMID 34575268, 2021). "This rapid appearance of IL-7R+ cells during tumorigenesis of pancreatic tumor indicates that IL-7R may be potentially useful as an early diagnosis marker for pancreatic cancer development." (PMID 34575268, 2021). "Our results suggest that IL-7R could be a potential marker for early pancreatic cancer diagnosis." (PMID 34575268, 2021). "To confirm the positive correlation between IL-7R expression in PBMC and the tumorigenesis of pancreatic cancer, we applied syngeneic mouse model of PDAC." (PMID 34575268, 2021). "Furthermore, the IL-7R, PLD4, and ID3 markers were statistically significant both in the univariate and multivariate models for differentiating pancreatic cancer from non-pancreatic cancer." (PMID 37165046, 2023). "IL-7R positive cells constituted 0.01% (range, 0.008–0.020) of normal PBMCs and 22.1% (range, 1.100–45.200) of PBMCs from pancreatic cancer patients." (PMID 34575268, 2021). "These several lines of evidence suggest that aberrantly elevated IL-7R may promote the differentiation and development of a variety of tumor, however, there is no study relating the level of IL-7R expression to the histopathological characteristics of pancreatic cancer to date." (PMID 34575268, 2021).
T-cell leukemia (5 papers, 2016 to 2022). A malignant disease of the T-lymphocytes in the bone marrow, thymus, and/or blood. "As a consequence, the overall structure remained intact and IL-7 cleaved by MMP-9 remained able to induce IL-7R internalization, to activate signal transduction through pSTAT3 and to induce cell proliferation in the human T cell leukemia cell line HPB-ALL." (PMID 34276694, 2021). "As well, activating mutations in IL7R occur in 10% of pediatric T-ALL cases, and transduction of mouse thymocyte progenitors with patient-derived IL7R mutants develop immature T-cell leukemias resembling human ETP T-ALL." (PMID 27532210, 2016). "Interestingly, activating mutations have been detected in the IL7-receptor gene IL7R, the mediating kinase JAK3, and its target protein STAT5B in T-cell leukemia." (PMID 28977998, 2017). "Adult T-cell leukemia cells were shown to be CD4+, CCR4+ and CD26− and patients who had aggressive disease were also CCR7 positive, whereas indolent patients were negative for both CCR7 and CD127 (interleukin 7 receptor α)." (PMID 35203305, 2022).
tuberculosis (5 papers, 2013 to 2021). A chronic, recurrent infection caused by the bacterium Mycobacterium tuberculosis. "We conclude that diminished soluble IL-7R and increased IL-7 plasma concentrations, as well as decreased membrane-associated IL-7R expression in T cells, reflect impaired T-cell sensitivity to IL-7 in tuberculosis patients." (PMID 28582466, 2017). "Therefore we questioned whether aberrant expression of IL-7R variants in tuberculosis patients is caused by differential regulation on the transcriptional or post-transcriptional level." (PMID 28582466, 2017). "Tuberculosis patients had lower soluble IL-7R (p < 0.001) and higher IL-7 (p < 0.001) plasma concentrations as compared to healthy contacts." (PMID 28582466, 2017). "Increased IL-7 and soluble IL-7R expression in pulmonary tissue of primates with tuberculosis was found, indicating a possible role of IL-7 metabolism in tuberculosis pathogenesis." (PMID 28582466, 2017). "None of the IL-7R variants were differentially expressed on the mRNA level of CD4+ T cells between tuberculosis patients and healthy contacts." (PMID 28582466, 2017). "Hence, we analysed IL-7R mRNA transcripts of purified CD4+ T cells from tuberculosis patients and healthy contacts." (PMID 28582466, 2017). "Here we investigated the role of IL-7/IL-7R on T-cell immunity in human tuberculosis." (PMID 28582466, 2017). "We concluded that increased frequencies of IL-7R rs6897932T alleles in tuberculosis patients contributed to differential sIL-7R levels but did not account for lower sIL-7R plasma concentrations of tuberculosis patients." (PMID 28582466, 2017). "However, a comprehensive understanding of the possible role of IL-7 or IL-7R functions in human tuberculosis has not yet been developed." (PMID 28582466, 2017).
allergic asthma (4 papers, 2011 to 2025). A asthma with a basis in a pathological type I hypersensitivity reaction. "Several new loci are relevant to immunological pathways (e.g., 5p13.2 near IL7R, 10p15.2 near IL2RA, and 22q12.3 near IL2RB), including the allergic asthma locus IL4R (ORCRSwNP = 1.151 [1.104–1.199], p = 2.54e-11)." (PMID 41213931, 2025).
atopic dermatitis (4 papers, 2011 to 2025). "For instance, the association of the TSLP SNP rs10073816 with atopic dermatitis persistence is strengthened when controlling for the IL7R SNP rs11567725." (PMID 39859044, 2025). "Rs10214237 T:T genotype was associated with an increased risk of atopic eczema in the population as a whole and in the sub‐population without dog exposure consistent with the T:T genotype showing slightly greater IL7R mRNA expression." (PMID 40462597, 2025). "IL7R variants have also been identified as risk factors for several diseases characterized by autoimmune or excessive immune and inflammatory responses, including multiple sclerosis, type 1 diabetes, and atopic dermatitis." (PMID 39859044, 2025). "IL-7R rs1053496 SNP displayed a protective role within CRC, like in atopic dermatitis." (PMID 34573368, 2021).